NLRP3 (NLR family pyrin domain containing 3)
Diseases named in the same sentence as NLRP3 in open-access papers (continued):
Sharing a sentence is not in itself a finding about the gene and the disease.
Arthritis (157 papers, 2008 to 2026). Inflammation of a joint. "The NLRP3 inflammasome is implicated in the pathogenesis of many nociceptive disorders, such as arthritis and neuropathic and inflammatory pain, as well as cancer-induced bone pain." (PMID 40002330, 2025). "Although the matching percentage between Terpinen-4-ol-targeted genes and the gouty arthritis gene set was only 9.5%, the common genes were highly linked with the 8 nodes and 28 edges around NLRP3." (PMID 39861092, 2024). "In recent years, there has been a growing interest in the associations between arthritis and NLRP3-mediated pyroptosis." (PMID 37954594, 2023). "C5aR2 has also been implicated in inflammatory processes, including NLRP3 inflammasome regulation in macrophages and regulation of neutrophilic inflammation in epidermolysis bullosa acquisita and arthritis." (PMID 38067135, 2023). "Anti-inflammatory cytokine IL-10-deficient mice exhibit severe antigen-induced arthritis with the upregulated expression of IL-1β and NLRP3 in the synovium." (PMID 35628185, 2022). "Deletion of the Pycard gene (encoding ASC) protected CIA mice from developing arthritis and bone erosion showing the importance of canonical inflammasomes; however, Nlrp3 and Casp1 null mice developed comparable disease to WT mice." (PMID 35567665, 2022). "As ERAP1 polymorphisms have been linked with inflammatory arthritic disease ankylosing spondylitis, we wished to study the role of ERAP1 in relation to the NLRP3 inflammasome specifically in arthritis-linked disorders." (PMID 35246034, 2022). "ASC knockout (ASC-/-) mice are protected from arthritis, while caspase-1 knockout (caspase-1-/-) and NLRP3 knockout (NLRP3-/-) mice are susceptible to CIA." (PMID 35095918, 2021). "In combination with the proband's clinical presentations, including periodic fever after exposure to cold, urticaria, arthritis, headache, and hearing loss, the diagnosis of NLRP3-AID was made." (PMID 34249981, 2021). "Humanized mice carrying an NLRP3 mutation (D305N/D305N mice) developed arthritis and osteoporosis shown by increased radiolucency and thinner cortices in all bones of the lower hindlimb compared to control animals." (PMID 31795299, 2019). "Humanized mice expressing disease-associated mutations in NLRP3 develop normally but acquire progressive and debilitating arthritis with age." (PMID 28978351, 2017). "While the NLRP3 inflammasome has been linked to arthritis progression, little is known about its synovial regulation or contribution to joint histopathology." (PMID 25175678, 2014). "Of those pathways, Fc receptors and β2 integrins are well known for their role in the K/BxN serum–transfer arthritis, and various forms of arthritis have also been associated with C-type lectins and the NLRP3 inflammasome." (PMID 20201079, 2010). "RIPK3 in IAP-deficient mice promotes autoantibody-mediated arthritis by promoting NLRP3 inflammasome formation and IL-1β release, which may be a consequence of RIPK3 inhibition of necroptosis by shifting the form of cell death to pyroptosis." (PMID 35464445, 2022). "Additionally, the overexpression of the NLRP3 inflammasome aggravates inflammatory osteolysis, causing arthritis, osteomyelitis and periodontal disease." (PMID 36359010, 2022). "Remarkably, it has been observed how a genetic modification that predisposes to the development of arthritis in mice results in greater activation of the NLRP3 inflammasome complex and likewise, the deletion of a functional NLRP3 complex produces notable improvements in the disease." (PMID 35740048, 2022). "Humanized mice expressing NLRP3 disease-associated mutations develop normally but show acute sensitivity to endotoxins and develop progressive and debilitating arthritis characterized by granulocytic infiltration, elevated cytokines, bone erosion, and osteoporosis." (PMID 35628185, 2022).
Arthritis (continued). "Similarly, Schnitzler syndrome, a rare autoimmune disease characterized by joint pain and arthritis, was linked to rare NLRP3 gene mutations and increased IL-1β release, and treatment with anakinra caused pain regression in six male patients." (PMID 32973552, 2020). "For example, NLRP3 and AIM-2 are both upregulated in the synovium of IL-10-deficient mice exposed to antigen-induced arthritis, and osteoclast differentiation from bone marrow cells isolated from these mutant mice is blunted by the inhibitors of NLRP3 and AIM-2 inflammasomes." (PMID 31520179, 2019). "This sequential cell death may be more crucial than NLRP3 inflammasome activation in the pathogenesis of crystal-induced chronic inflammation and fibrosis such as arthritis, silicosis, and asbestosis as these diseases develop in NLRP3-deficient mice." (PMID 29434606, 2018). "Experimental investigation showed that the expression of NLRP3 was positively correlated with the severity of arthritis in the synovium of CIA mice." (PMID 40732305, 2025). "The effects of various compounds on the NLRP3 inflammasome have also been reported in many other studies in various arthritis models." (PMID 39852153, 2025). "Western blot showed that Fuzi regulates TGR5-cAMP-PKA signaling and NLRP3 inflammasome to reduce cold-related arthritis." (PMID 40375326, 2025). "Concurrent with necroptosis, NLRP3 inflammasome hyperactivation emerges as a key driver of arthritis." (PMID 41583484, 2025). "We will test the effect of Cant on NLRP3 inflammasome activation in tissues of collagen-induced arthritis in future studies." (PMID 39852153, 2025). "In JIA-specific preclinical models (such as collagen-induced arthritis), this multi-target approach has been demonstrated to be effective, primarily by modulating inflammatory pathways like NLRP3/NF-κB." (PMID 41583480, 2025). "P2X7R was demonstrated to activate NLRP3 inflammasome to enhance collagen-induced arthritis in mice, and sinomenine exhibited therapeutic roles in collagen-induced arthritis by targeting the P2X7R-NLRP3 pathway." (PMID 38993566, 2024). "Many works revealed the implication of the NLRP3 inflammasome in the pathology of several peripheral disorders including arthritis, neuropathy, and inflammatory pain." (PMID 39061924, 2024). "Both patients with RA and experimental arthritis mouse models exhibit elevated IL-1β and NLRP3 levels." (PMID 39179640, 2024). "While extensive research confirms NLRP3 inflammasome involvement in the pathophysiology of arthritis and identifies potential inflammatory mechanisms, some interventions targeting these pathways have not transitioned successfully into clinical treatments." (PMID 38317229, 2024). "AB4 treatment inhibits spinal GSK‐3β activity, enhances Nrf2/GPX4 antioxidant response, reduces Drp1‐mediated mitochondrial ROS production, suppresses NLRP3 inflammasome activation and alleviates arthritis pain." (PMID 38334255, 2024). "In a drug experiment on resveratrol, the researchers revealed that resveratrol inhibited NLRP3 inflammasome activation by promoting mitophagy in a rat arthritis model, ultimately ameliorating arthritis symptoms." (PMID 38317229, 2024). "Considering these findings, we wonder if SDSS exerts anti-arthritis properties by inhibiting HIF-1α/STAT3/NLRP3 axis." (PMID 36838542, 2023). "Excessive activation of NLRP3 inflammasome drives the pathogenesis of arthritis in spontaneous arthritis animal models (A20 myel-KO mice)." (PMID 37063906, 2023). "This review provides an overview of the features and processes involved in the pyroptosis mediated by the NLRP3 inflammasome, emphasizing its crucial contribution to the development of arthritis." (PMID 37954594, 2023). "The mRNA expression of Kat2a in synovial macrophages from CIA model was also significantly higher after arthritis induction, which was strongly correlated with Nlrp3 expression in synovial macrophages." (PMID 37313329, 2023).
Arthritis (continued). "Several arthritis risky factors, such as metabolites, crystals, and mitochondrial dysfunction, can mediate the NLRP3 inflammasome activation and pyroptosis of synovial macrophages." (PMID 37422640, 2023). "In the synovium of collagen‐induced arthritis mice, NLRP3 expression was positively correlated with arthritis severity." (PMID 37386795, 2023). "In the past few years, there has been a growing interest in investigating the impact of cell pyroptosis on arthritis development, particularly the widespread occurrence of pyroptosis mediated by the NLRP3 inflammasome." (PMID 37954594, 2023). "This is the first in vivo and in vitro evidence that SDSS exerts its role in ameliorating arthritis through suppressing the HIF-1α/STAT3/NLRP3 pathway, therefore modulating the inflammatory activation in macrophages." (PMID 36838542, 2023). "The model demonstrates an apparent augmentation in the expression of NLRP3 inside synovial tissues, exhibiting a favorable correlation with both clinical and radiographic assessments of arthritis." (PMID 37960237, 2023). "Among the drug treatment strategies for arthritis, drugs that directly block and indirectly affect the NLRP3-mediated pyroptosis pathway can be classified according to their different activation types." (PMID 37954594, 2023). "For example, excessive Nlrp3 inflammasome activation drives arthritis pathogenesis in A20 knockout mice due to A20 putting a brake on Nlrp3 inflammasome activation by reducing LPS-induced Nlrp3 expression levels." (PMID 36726689, 2023). "GSK-3β inhibitor TDZD-8 treatment suppresses spinal Bax and DHODH mediated mitochondrial ROS levels, inhibits NF-κB mediated NLRP3 inflammation activation, and alleviates arthritis pain." (PMID 37058473, 2023). "Enrichment of GGC following the change of microbiota activates suppress arthritis via inhibiting NLRP3 inflammasome activation." (PMID 36417588, 2023). "Together, the host must tightly control NLRP3 to prevent excessive activation of NLRP3 inflammation, which can lead to chronic or systemic inflammatory conditions like arthritis." (PMID 37954594, 2023). "In mouse models of arthritis, the presence of extracellular acidosis triggers the activation of NLRP3-mediated pyroptosis in chondrocytes." (PMID 37960237, 2023). "Compelling evidence has described that NLRP3 inflammasome, and in turn IL-1β secretion, are highly activated in both RA patients and arthritis preclinical models in several type of RA cells (macrophages or monocytes, CD4+T cells, Th17 and synoviocytes)." (PMID 35740048, 2022). "Artemisinin inhibits LPS- and MSU-induced NEK7 and NLRP3 expression levels in macrophages and attenuates K+ efflux from macrophages to reduce foot and ankle swelling in mice with arthritis." (PMID 35464445, 2022). "In animal investigations, inhibition of NLRP3 and caspase-1 was also found to be useful in alleviating the symptoms of arthritis in RA (CIA mouse model)." (PMID 36532040, 2022). "Expression of NLRP3, caspase-1, and IL-1 is increased in the synovial tissues of CIA mice, and IL-1α, IL-1β, and IL-1αβ-deficient mice are less sensitive to CIA-induced arthritis." (PMID 35628185, 2022). "In arthritis rat models, resveratrol inhibits the activation of NLRP3 inflammasomes by inducing the PINK1/Parkin-dependent mitophagy." (PMID 35874841, 2022). "And, IL-37 treatment ameliorates temporomandibular joint inflammation via inhibiting the expression of NLRP3 and IL-1β, which can be reversed by knockdown of IL-1R88." (PMID 36418383, 2022). "As an effective arthritis inhibitor, GlcN has been proved to suppress the activation of nucleotide-binding oligomerization domain-like receptor containing pyrin domain 3 (NLRP3) inflammasome in mouse and human macrophages." (PMID 34149435, 2021). "A later study demonstrated synovial NLRP3 expression level was correlated with the clinical arthritis severity and extent of radiological destruction, suggesting that NLRP3 is involved in the pathogenesis of RA." (PMID 34750358, 2021).
Arthritis (continued). "A collagen-induced arthritis (CIA) model was constructed to investigate the effect of TOF on arthritis symptoms, γδTreg/γδT17 cell balance and the NLRP3 inflammasome." (PMID 33391544, 2021). "It was reported that the expression of NLRP3, IL-18, and IL-1β in joint synovial fluid was significantly increased in mice with collagen-induced arthritis, and the expression of NLRP3 was correlated with the severity of clinical arthritis." (PMID 33430857, 2021). "Delivery of MSU into the abdominal cavity and the joints resulted in NLRP3-dependent IL-1β production and neutrophil influx and NLRP3-dependent arthritis, respectively." (PMID 34745110, 2021). "Osteoporosis and arthritis were detected in Nlrp3(D305N) mice in comparison with wild type (WT) mice, providing an NLRP3-dependent arthritis model platform for testing therapeutic agents against inflammasomes." (PMID 33215255, 2021). "It has been reported that the NLRP3 inflammasome is activated in the synovium of RA mice, and that treatment with a selective NLRP3 inhibitor can reduce the symptoms of arthritis and cartilage destruction." (PMID 34583676, 2021). "The expression of synovial NLRP3 was positively correlated with clinical and radiographic arthritis scores in the CIA model in mice; however, the synovial tissue, which was analyzed in that study, contains several cell types." (PMID 35126351, 2021). "Investigation of NLRP3 activation in synovial tissues from RA and osteoarthritis patients and in rodent model of collagen-induced arthritis treated with MCC950." (PMID 32973552, 2020). "In the current study, using two distinct murine models of acute inflammatory arthritis, we validated the rationale for treatment of acute joint inflammation with the NLRP3 inflammasome inhibitor OLT1177." (PMID 30075804, 2018). "This is the first study that shows that the extent of synovial NLRP3 expression is correlated with the clinical severity of arthritis and radiological scores." (PMID 27034595, 2016). "The increased synovial and serum NLRP3 expressions strongly suggest that the NLRP3 is involved in pathogenesis of arthritis." (PMID 27034595, 2016). "The expression of synovial NLRP3 was positively correlated with arthritis clinical and radiographic scores (r = 0.792 and r = 0.669, resp)." (PMID 27034595, 2016). "In our future study, we will increase the sample size and apply more experimental/analytical method to further study the relationship between the NLRP3 expression in synovial tissue and arthritis pathogenesis." (PMID 27034595, 2016). "Synovial NLRP3 expression level was correlated with the clinical arthritis severity and extent of radiological destruction, suggesting that NLRP3 is involved in the pathogenesis of RA." (PMID 27034595, 2016). "The arthritis score (6.00 ± 2.52), imaging score (4.63 ± 0.92), and synovial tissue NLRP3 expression (4.00 ± 2.03) significantly increased in the CIA mice." (PMID 27034595, 2016). "Our study is the first one that analyzed the correlation of serum and joint NLRP3 expressions and arthritis clinical and radiographic scores." (PMID 27034595, 2016). "This study shows the relationship between NLRP3 and arthritis; however, the animal sample size is small and experimental and analytical methods have limitations." (PMID 27034595, 2016). "have shown that arthritis pathology is critically related to the NLRP3 inflammasome/IL-1 signaling axis, in the arthritis model A20myel-KO mice, in which the A20/Tnfaip3 RA susceptibility gene is deleted in myeloid cells." (PMID 26385789, 2015). "A20 plays a central role in the control of NF-kB activation, A20 also negative regulates NLRP3 inflammasome to protect against arthritis." (PMID 26143186, 2015). "Here, we show that IL-10 negatively regulates the expression of NLRP3 inflammasome components within the inflamed synovium of experimental arthritis and provide a link to degenerative bone erosion." (PMID 25175678, 2014).
Arthritis (continued). "In contrast to caspase-1 and NLRP3 deficient mice, ASC deficient mice were completely protected from the development of arthritis in a collagen induced arthritis study." (PMID 22216309, 2011). "Similarly, mice with antigen-induced arthritis showed severe joint inflammation and increased expression of IL-1β and NLRP3 inflammasome in the synovial membrane." (PMID 40732305, 2025). "Therapeutic strategies targeting both mechanisms—such as combined necroptosis inhibitors and NLRP3 antagonists—may offer enhanced efficacy in mitigating arthritis progression." (PMID 41583484, 2025). "In addition, the protein expression levels of RASGRF1 and NLRP3 were reduced by CEL in WT arthritis mice." (PMID 41164801, 2025). "Moreover, RASGRF1 and NLRP3 protein expression was lower in the synovial tissue of the IGF2BP3-KO arthritis mice than in that of the WT arthritis mice." (PMID 40355406, 2025). "It is reported that NOD-like receptor thermal protein domain associated protein 3 (NLRP3) inflammasome triggered by TGR5-cAMP-PKA axis play a direct role in arthritis inflammation, we therefore further determined the levels of NLRP3, ASC, caspase-1 p20, and IL-1β p17." (PMID 40375326, 2025). "It has been implicated in the modulation of NLRP3 cytokine secretion but not investigated for a pathogenic role in arthritis." (PMID 41013715, 2025). "Overactivation of the NLRP3 inflammasome can cause systemic inflammation, including recurrent fever, urticaria-like rashes (with or without cold exposure), arthritis, aseptic meningitis, hearing loss, mental and growth retardation, and bony overgrowth." (PMID 40852416, 2025). "In this study, we demonstrated that deZP for pharmacopuncture reduced IL-1β levels and suggested that this effect may be mediated by the NLRP3 inflammasome signal pathway in a gouty arthritis mouse model." (PMID 39861092, 2024). "Furthermore, treatment with the NLRP3 inhibitor MCC950 alleviates the severity of arthritis in mouse models, indicating the pivotal role of the NLRP3 inflammasome in RA pathogenesis." (PMID 39179640, 2024). "In the present study, the mRNA level of caspase-1 in NLRP3 inflammasome was significantly downregulated in Stefin B-overexpressed GA mice, accompanied by a decreased serum IL-17 level, which is closely correlated to arthritis." (PMID 38294507, 2024). "Therefore, the NLRP3 pathway plays a role in inducing inflammatory reactions and chondrocyte apoptosis, and inhibiting NLRP3 can treat iron overload-induced arthritis using CAR." (PMID 38178210, 2024). "Targeting miRNAs to regulate NLRP3-mediated pyroptosis in arthritis." (PMID 37954594, 2023). "Targeting the NLRP3-mediated pyroptosis could hold great promise for anti-inflammatory treatments of arthritis." (PMID 37954594, 2023). "In this way, we speculated whether KAT2A played a role in NLRP3 gene expression in inflammatory macrophages and arthritis." (PMID 37313329, 2023). "Drugs targeting NLRP3 inflammasome mediated pyroptosis in arthritis." (PMID 37954594, 2023). "Therefore, we summarize recent studies related to miRNAs/NLRP3 signaling with function of regulating the development of arthritis." (PMID 37954594, 2023). "Furthermore, we provide a summary of the advancements made in studying the NLRP3 inflammasome in various forms of arthritis and enumerate the intervention approaches that target the NLRP3-mediated pyroptosis, either directly or indirectly." (PMID 37954594, 2023). "Consequently, the etiology of arthritis in A20myel-KO mice is attributed to the excessive activation of NLRP3 inflammasome." (PMID 37954594, 2023). "Interestingly, A20 has been shown to inhibit NF-κB signaling pathway and NLRP3 inflammasome activation as well as autophagy, thereby preventing pulmonary fibrosis and arthritis." (PMID 36726689, 2023). "Furthermore, we offer an extensive analysis of the potential medications targeting NLRP3-mediated pyroptosis as a therapeutic approach for arthritis." (PMID 37954594, 2023).